SMYD3 (SET and MYND domain containing 3)
Diseases named in the same sentence as SMYD3 in open-access papers (continued):
Sharing a sentence is not in itself a finding about the gene and the disease.
cancer (continued). "SMYD3 (SET and MYND domain‐containing 3) is a histone lysine methyltransferase highly expressed in different types of cancer(s) and is a promising epigenetic target for developing novel antitumor therapeutics." (PMID 39286779, 2024). "SMYD3 promotes S1PR1 expression by promoting histone methylation in the S1PR1 promoter region, thereby promoting the progression of malignant tumors." (PMID 36611207, 2023). "In line with this view, here we showed that SMYD3 is part of a multiprotein complex comprising AMPK and mTOR in cancer cells exposed to DNA-damaging drugs." (PMID 37998381, 2023). "Additional screening revealed that SMYD3 was robustly upregulated in OSCC tissues, especially cancer cells, and the ROC curves showed promising results." (PMID 37237385, 2023). "IHC staining revealed that SMYD3 was overexpressed in OSCC tissues and the protein expression increased as the malignant tumors progressed." (PMID 37237385, 2023). "SMYD3 was initially defined as a H3K4 methyltransferase to promote H3K4me3 formation and activate downstream gene transcription to participate in cancer development." (PMID 37237385, 2023). "This evidence highlights the crucial role played by SMYD3, TRRAP, and EP300 in cancer-related epigenetic reprogramming processes." (PMID 37954147, 2023). "Surprisingly, this computational tripeptide screening of the human proteome allowed us to identify crucial cancer-related proteins such as mTOR, BLM, MET, AMPK, and RBL2 (p130) as novel SMYD3 interactors." (PMID 36496998, 2022). "To directly explore a role for SMYD3 in SCLC responses to chemotherapy, we generated conditional Smyd3LoxP/LoxP-mutant mice crossed with the TKO cancer model (TKO; Smyd3)." (PMID 35819319, 2022). "In this light, identifying the SMYD3 regions that interact with P-proteins and using purified P-tripeptides to interfere with these physical interactions may offer a potential avenue to develop anticancer therapeutics and/or to resensitize resistant cancers to chemotherapeutic DNA-damaging agents." (PMID 35495117, 2022). "Herein, we dissect the unique structural features of SMYD3 relative to other SET enzymes, with an emphasis on the implications for selective design of therapeutics for the clinical management of cancer." (PMID 35076487, 2021). "Recently, SMYD3 was shown to methylate the MAP3K2 and the AKT kinase and affect the Ras-activated pathway in certain types of cancer." (PMID 34069776, 2021). "SMYD3 (SET and MYND domain containing protein 3) is a methylase over-expressed in cancer cells and involved in oncogenesis." (PMID 34069776, 2021). "ChIP- and RNA-Seq assays showed that SMYD3 directly regulates Myc and Ctnnb1 oncogenes, as well as components of the IL6-Jak-Stat3 oncogenic cascade and other cell proliferation and cancer-related genes, in liver and colon carcinogenesis." (PMID 31935919, 2020). "The SMYD3/HER2 link is clinically relevant because of the abnormal HER2 activation involved in development and progression of various types of cancers: namely, HER2 amplification is observed in 18–25% of BrCA and correlates with poor prognosis." (PMID 31935919, 2020). "SET and MYND domain-containing protein 3 (SMYD3), a histone methyltransferase, is a promising epigenetic therapeutic target and has been found to be upregulated in a variety of human cancers." (PMID 32742495, 2020). "Second, SMYD3-mediated methylation of MAP3K2 at lysine 260 potentiates activation of the Ras/Raf/MEK/ERK signaling module and promotes the formation of Ras-driven carcinomas." (PMID 32007952, 2020). "Methylation of MAP3K2, a mitogen-activated protein kinase, links SMYD3 to the MAPK signaling pathway and Ras-driven cancer." (PMID 31737645, 2019). "Until now, many oncogenes have been demonstrated to be regulated on transcriptional level by SMYD3 through trimethyl-H3K4 (H3K4me3) modification, which highlights the role of SMYD3 as an essential epigenetic regulator in cancer cells." (PMID 30646949, 2019).
cancer (continued). "As a histone methyltransferase, SMYD3 had been repeatedly reported that promotes target genes expression by binding to its promoter and methylating H3K4 in multiple cancers." (PMID 31417652, 2019). "Therefore, drug intervention of SMYD3 may be beneficial to the fields of cancer." (PMID 28050603, 2017). "SET and MYND domain-containing protein 3 (SMYD3), a dimethyltransferase and trimethyltransferase, are significantly up-regulated in several cancers." (PMID 27501725, 2016). "In the present study, we demonstrate that SMYD3 methylates lysine residues in the PH domain of AKT1, and this methylation is essential for AKT1 activation in human cancer cells." (PMID 27626683, 2016). "To test this possibility, we depleted SMYD3 in two bladder (J82 and T24) and two colon (HCT116 and CaCO2) cancer cells expressing high levels of SMYD3." (PMID 26350217, 2015). "Finally, to evaluate the clinical relevance of c-MYC methylation by SMYD3, we assessed c-MYC K158/K163Me levels by immunohistochemistry in normal and cancer tissues from CRC patients with advanced-stage cancer." (PMID 40588481, 2025). "Furthermore, while the pattern of protein expression in cancer cells of HPV-negative HNSCC tumors was predominantly cytoplasmic, nuclear speckles were also observed, supporting the presence of SMYD3 in the nucleus of HPV-negative HNSCC cancer cells." (PMID 39762343, 2025). "In our case, a positive score indicates a higher expression of the gene in EM127-treated CRC-SCs from patients with SMYD3-overexpressing cancers compared to untreated cells, while a negative score denotes a lower gene expression." (PMID 40588481, 2025). "Although there is a small molecule SMYD3 inhibitor that is considered to have good bioavailability, or others can inhibit cancer cell proliferation, currently, no molecules targeting SMYD3 have been reported to be used in clinical cancer treatment." (PMID 39286779, 2024). "Importantly, we found that SMYD3 pharmacological inhibition with the novel compound EM127 reverses chemoresistance, making cancer cells more sensitive to CHT exposure." (PMID 38812026, 2024). "SMYD3 methylates both histone and non-histone proteins, thereby orchestrating their interactions and functions, and is involved in cancer-related pathways." (PMID 37998381, 2023). "To gain further insight into the role of SMYD3 in cancer-related epigenetic processes, we investigated in depth the interaction between SMYD3 and specific P-proteins involved in the emerging ‘nonmutational epigenetic reprogramming’ cancer hallmark." (PMID 37954147, 2023). "In this light, our results suggest that targeting the SMYD3 methyltransferase to disrupt the signaling balance between AMPK and mTOR in cancer cells may represent a suitable therapeutic approach." (PMID 37998381, 2023). "Besides, several methyltransferases like SMYD3, EZH2, and SETDB1 are also abnormally expressed in common human cancer lines." (PMID 37220590, 2023). "Computational analysis of publicly available gene-expression data revealed that SMYD3 is particularly highly expressed in neuroendocrine lung cancer subtypes [SCLC and large cell neuroendocrine lung cancer (LCNE)] compared with other cancer subtypes and normal lung epithelium." (PMID 35819319, 2022). "The small-molecule inhibitor BCI-121 selectively targets SMYD3-substrate interactions and has been extensively studied in other cancers; however, its efficacy in MB has not been investigated." (PMID 35406445, 2022). "In response to metabolic stress, SMYD3 could interact with AMPK, the main effector of cancer cell metabolic reprogramming." (PMID 35495117, 2022).
cancer (continued). "In this review, we provide an overview of the literature pertaining to SMYD3, its reported histone and non-histone functions, implications in cancer, and drug discovery possibilities." (PMID 33637115, 2021). "In normal tissues, SMYD3 expression is low or absent, while in cancers, SMYD3 is significantly overexpressed." (PMID 33637115, 2021). "Increased TERT mRNA levels were observed after overexpression of SMYD3, while its suppression led to reduced H3K4 trimethylation within the TERT core promoter and also decreased the ability of MYC and SP1 to bind the promoter in cancer cell lines." (PMID 33802026, 2021). "Based on these findings, the authors concluded that SMYD3 is not required for autonomous proliferation of cancer cells in vitro." (PMID 34503239, 2021). "Besides, SMYD3 was reported to methylate K14 of AKT1 and K175 of HER2 to enhance their respective activations through autophosphorylation in cancer cells." (PMID 34281237, 2021). "As its methyltransferase activity on nonhistone targets involves tumorigenesis, SMYD3 has drawn attention for its role in cancer progression and invasion." (PMID 34281237, 2021). "MGAT4C, HSPA4L, ZSCAN5A, LOC100505841, and NALCN gene deletions were associated with cancer patients without FCH (p < 0.05), while SMYD3 and NKD2DSV genes were associated with cancer patients with FCH (p < 0.05)." (PMID 33431054, 2021). "While several studies uncovered key functions for SMYD3 in cancer models, the SMYD3 role in physiological conditions has not been fully elucidated yet." (PMID 34069776, 2021). "SMYD3 binds specific DNA sequences and activates the transcription of target genes such as matrix metalloprotease-9 (MMP), a critical protein for maintaining cancer status." (PMID 33557100, 2021). "Besides its H3K4 methyltransferase activity, Smyd3 can also catalyze the methylation of H4K5 and H2A.Z, which function in cancer cell growth and other related phenotypes." (PMID 32779886, 2020). "Interestingly, hemizygous knockout of SPRIGHTLY by CRISPR/Cas9 in cancer cells significantly decreases SPRIGHTLY lncRNA levels, simultaneously decreasing the levels of its interacting SMYD3 pre-mRNA molecule and anchorage-independent growth rate of cells." (PMID 31935919, 2020). "SMYD3 methylation-dependent functions include its ability to methylate non-histone proteins, which are involved in the cancer cell survival and proliferation." (PMID 31935919, 2020). "SMYD3 was initially described as a H3K4 methylase, involved in cancer cell proliferation." (PMID 31935919, 2020). "Studies have shown that SMYD3 plays an important role in the development of tumors and is highly expressed in many cancer cells but not in the corresponding normal tissues." (PMID 31968646, 2020). "In addition, as a H3-K4 methyltransferase, SMYD3 trans-activates many genes, including MMP-9, Bcl-xL, WNT10B, and Nkx2.8, all of which play critical roles in cancer development and/or progression." (PMID 32007952, 2020). "We revealed for the first time that manipulation of Smyd3 can contribute to cellular senescence but not cancer in endothelial cells." (PMID 32779886, 2020). "The data presented in this work offer strong evidence that in contrast to some of the literature, SMYD2 and SMYD3 are not required for cancer proliferation in vitro." (PMID 29856759, 2018). "Based on these findings, we conclude that despite previous observations using RNAi based techniques and early stage chemical probes, SMYD2 and SMYD3 are not required for autonomous proliferation of cancer cells." (PMID 29856759, 2018). "Nevertheless, and in contrast to many of the earlier studies summarized above, these SMYD2 and SMYD3 inhibitors show no impact on the cell proliferation of more than 240 cancer cell lines regardless of genetic or histological background." (PMID 29856759, 2018).
cancer (continued). "MTT and cell invasion assays also showed that SMYD3 depletion decreased the proliferation and invasion of HCT116 cancer cells and that the expression of SMYD3 wild-type, but not SMYD3 F183A mutant, restored cell proliferation and invasion rates." (PMID 26350217, 2015). "The protein methyltransferase SET and MYND domain-containing 3 (SMYD3), which trimethylates H3K4, activates gene transcription and enhances several oncogenic pathways, including epithelial-mesenchymal transition and cell cycle related pathways, in various cancer types." (PMID 39762343, 2025). "E2/ERα-SMYD3, SHCBP1, H3K4me3 and Kras-MAPK in all developmental stages of mammary tissues in the Brca1MKO mouse and parous mammary epithelial cells and serve as a cancer driver in general, although a stronger effect is observed in early pregnancy because of the higher levels of E2/ERα signaling." (PMID 40157910, 2025). "Indeed, cancer cells lacking SMYD3 functions showed increased responsiveness to CHTs, while restoring its expression promoted chemoresistance." (PMID 38812026, 2024). "However, the molecular pathway through which it drives cancer progression has not been fully defined in many of the cancers with SMYD3 overexpression." (PMID 37976356, 2023). "Furthermore, since SMYD3 has been reported to modulate an ATM-related pathway in GC cells, it may also be involved in DDR processes in this cancer type, as has already been observed in other tumors, thus gaining ground as an interesting therapeutic target." (PMID 37894343, 2023). "However, a recent report on hundreds of cancer cell lines of different origins and genetic backgrounds showed that SMYD3 genetic ablation or pharmacological blockade does not impair autonomous cancer cell proliferation." (PMID 35495117, 2022). "This review aims to provide a background on basic characteristics of SMYD3, such as its protein structure and tissue expression profiles, discuss reported histone and non-histone substrates of SMYD3, and underscore prognostic and functional implications of SMYD3 in cancer." (PMID 33637115, 2021). "SMYD3 methylates not only histone H3 at lysine 4 but also histone H3 at lysine 9, histone H4 at lysine 5, and histone H4 at lysine 20; these histone lysine methylation events meditated by the SET domain of SMYD3 exert significant effects on cancer development and progression." (PMID 34301921, 2021). "Among the numerous lysine methylases, SMYD3 represents an interesting example because it plays a significant role in cancer progression and invasion, both methylating several non-histone proteins involved in tumorigenesis and affecting transcriptional regulation." (PMID 31935919, 2020). "Moreover, Smyd3 has the capacity to modify non‐histone proteins VEGFR and MAP3K2 to promote metastasis and Ras/Raf/MEK/ERK signaling in cancer development." (PMID 32779886, 2020). "Overall, these data imply that SMYD3-mediated methylation of AKT1 at lysine 14 is essential for AKT1 activation and suggest that the inhibition of this methylation pathway may be a promising strategy to develop anti-cancer drugs." (PMID 31935919, 2020). "In order to examine whether SMYD3 mRNA is upregulated in cancer stages as seen in other cancers, we analyzed the expression of SMYD3 mRNA in HCC tissue specimens and in adjacent non-tumor liver tissues obtained from 48 HBV-related HCC patients." (PMID 32071406, 2020). "Our findings may suggest that SMYD3 is likely to be an important target for development of a novel class of anti‐cancer drugs." (PMID 28639750, 2017). "Although not an S-phase gene, SMYD3 has been identified as essential for cancer cell proliferation." (PMID 28228757, 2017). "Besides, we confirmed that the SMYD3 inhibitor BCI-121 significantly diminished Thr 308 phosphorylation levels of AKT1; this inhibitor effectively repressed the growth of cancer cells overexpressing SMYD3, further supporting the potential of SMYD3 as a target of anti-cancer drug development." (PMID 27626683, 2016).
cancer (continued). "To further explore the biological functions of SMYD3 in human cancer, we performed liquid chromatography tandem-mass spectrometry (LC-MS/MS) analysis of AKT1 protein and identified that lysines 14, 30 and 39 (Lys 14, Lys 30 and Lys 39) in the PH domain of AKT1 were possibly methylated by SMYD3." (PMID 27626683, 2016). "Thus, targeting therapeutic intervention to cooperative activity of SMYD3 and PC4 could provide effective strategy for cancer treatment." (PMID 26350217, 2015). "Clearly, the ability to prevent reversion to a more pluripotent state in the first place may suffice to significantly reduce the short term threat from cancers, suggesting the interaction between HSP90 and epigenetic proteins such as SMYD3 needs a closer inspection." (PMID 25738358, 2015). "Unlike SMYD3 wild-type, PC4 binding-deficient SMYD3 mutant failed to recover the proliferation and invasiveness of SMYD3-depleted cancer cells, thus demonstrating that SMYD3-mediated recruitment of PC4 is critical for SMYD3 function at genes involved in cell proliferation and invasion." (PMID 26350217, 2015). "Thus, to confirm the direct contribution of SMYD3 in mediating cancer cell responsiveness to genotoxic drugs, we transiently restored SMYD3 expression in HCT116-SMYD3-KO cells with a construct leading to the synthesis of WT SMYD3 (FLAG-SMYD3-WT) or an enzymatic-inactive mutant (FLAG-SMYD3-F183A)." (PMID 38812026, 2024). "Additionally, pharmacologic inhibition of other methyltransferases (e.g., PRMT5, SMYD3, or MLL4 methyltransferase) or specific deletion of these epigenetic regulators in cancer cells has also been found to specifically increase the antitumor efficacy of anti-PD1 therapy across cancer types." (PMID 39133578, 2024). "In addition, SMYD3 can methylate lysine 14 on the AKT1 kinase, which promotes its phosphoactivation and plasma membrane accumulation, suggesting that SMYD3 methyltransferase activity may trigger the constitutive activation of AKT1 in cancer cells." (PMID 34503239, 2021). "Our results imply that SMYD3‐mediated methylation of HER2 at Lysine 175 may regulate the formation of HER2 homodimer and subsequent autophosphorylation and suggest that the SMYD3‐mediated methylation pathway seems to be a good target for development of novel anti‐cancer therapy." (PMID 28639750, 2017). "In this study, we show that SMYD3 also exerts non-immune mediated, direct oncogenic effects in HPV-negative HNSCC cancer cells and tumors." (PMID 39762343, 2025). "In contrast, higher expression of SMYD3 was not evident in breast (MCF7 and MDA-MB-231) and prostate (LNCaP and DU145) cancer cell lines compared to normal cell lines (MCF-10–2A and MLC)." (PMID 26350217, 2015).